TNF (tumor necrosis factor)
Diseases named in the same sentence as TNF in open-access papers (continued):
Sharing a sentence is not in itself a finding about the gene and the disease.
psoriasis (continued). "Anti-TNF-α monoclonal antibodies (infliximab, adalimumab, golimumab, and certolizumab pegol) revolutionised therapy for many chronic inflammatory disorders, including psoriasis." (PMID 33926088, 2021). "Psoriasis and depression can lead to the dysregulation of the gut microbiota, induce gut permeability and bacterial migration, then increases pro-inflammatory cytokines such as IL-β, IL-6, TNF-α and IFN-γ." (PMID 35004741, 2021). "This region was also noted to affect the response to anti-TNF therapy outcome in psoriasis." (PMID 34744511, 2021). "Moreover, sensors can cure psoriasis through sensing TNF-a and IL-22 as biomarkers of psoriasis with the following expression of the therapeutic cytokines IL-4 and IL-10." (PMID 34829757, 2021). "Plaque-type psoriasis is characterised by the inflammatory pathway TNFα–IL-23–Th17." (PMID 34067151, 2021). "It has been reported that patients with IBD who were treated with TNF-α inhibitors may develop paradoxical psoriasis." (PMID 33810197, 2021). "Drugs that systemically inhibit TNF-α, IL-17 and IL-23 cytokines such as infliximab, secukinumab, and ustekinumab have been proved to be effective and safe therapeutic agents for the treatment of psoriasis." (PMID 34381369, 2021). "Nevertheless, previous studies have shown that also topical administration of TNF blockers might have efficacy in psoriasis." (PMID 34336906, 2021). "When TNF-α binds to its receptor, it can initiate the NF-κB signaling pathway to regulate the transcription of various cytokines, chemokines, adhesion molecules and enzymes, and aggravate the inflammatory response of psoriasis." (PMID 33613635, 2021). "However, there are reports of new-onset or exacerbation of psoriasis occurring after anti-TNF-α therapy; this condition is known as paradoxical psoriasis." (PMID 34790055, 2021). "TNF-α increases the production of pro-inflammatory cytokines including IL-1 and IL-6, and activates the NF-κB-signaling pathway, which promotes the development of psoriasis." (PMID 34679744, 2021). "This correlative presence of Reg-3 and TNF in psoriatic skin further suggests that Reg-3 may serve as a regulator of TNF levels in psoriasis." (PMID 34298932, 2021). "Here we demonstrate that Reg-3 transcript levels are increased in psoriasis patient skin tissue and in an experimental model of psoriasis, supporting the immunomodulatory role of Reg-3 in psoriasis, possibly through degradation of mRNA for TNF and other factors such as Reg-1." (PMID 34298932, 2021). "Moreover, the production of I-IFN by plasmacytoid dendritic cells is controlled by TNF level; so anti-TNFα treatment causes an overexpression of I-IFN, which is linked to paradoxical psoriasis." (PMID 34680599, 2021). "However, there is no conclusive evidence to prove the specific therapeutic effect of TNF-α inhibitors on CHF in psoriasis patients." (PMID 34803716, 2021). "TNF-α-antagonists have been extensively employed for treating psoriasis." (PMID 34678884, 2021). "TNF-α is a key inflammatory cytokine in psoriasis produced by Th1, Th17 cells." (PMID 34884596, 2021). "As of the writing of this study, the list of commercially available biologic agents for psoriasis is constantly growing, including, but not limited to, inhibitors of tumor necrosis factor (TNF), interleukin (IL)-17 receptor, IL-17, IL-12/23, IL-23, phosphodiesterase, and Janus kinases." (PMID 34977058, 2021). "Psoriasis is more common in smokers/ex-smokers of IBD that were treated with TNF-antagonists." (PMID 34678884, 2021). "They demonstrated that the incubation of macrophages with GNPs significantly reduced the production of IL-12, TNF-α, and NO through suppressing NF-κB activation and substantially reduced inflammatory macrophages and TNF-α and IL-12 production in human psoriasis plaques." (PMID 34572503, 2021).
psoriasis (continued). "TNF-α is a pro-inflammatory cytokine that activates the endogenous inflammatory cascade, and it is responsible in chronic inflammation as periodontitis and psoriasis." (PMID 33603725, 2021). "Furthermore, the ELISA data showed that the pro-inflammatory mediators including IL-6, IL-17A, IL-23, IL-24, and TNF dramatically increased in psoriasis-like mice intervened by shLuc." (PMID 34638757, 2021). "Therefore, we examined the possible correlation of key cytokines (IL-1β, TNF-α, IL-4, and IL-6) known to drive crosstalk between KCs and immune sentinels, which results in psoriasis development, with the induction of miR-21-5p or miR-21-3p expression." (PMID 34685526, 2021). "Therefore, our in vitro psoriasis model using primary keratinocytes isolated from the skin of healthy donors treated with a combination of IL-17A, IL-22 and TNF-α provides an interesting substitute model that has already proven its capability." (PMID 34641358, 2021). "Many previous studies revealed that psoriasis is an inflammatory disease, and patients with this disease may have higher serum levels of cytokines, such as tumour necrosis factor (TNF)-α, interferon (IFN)-γ, (interleukin (IL)-6, IL-8, IL-12, IL-17 and IL-18." (PMID 34290604, 2021). "Therefore, quercetin combined with microneedles can be applied to treat psoriasis by reducing the expression of IL-17 and TNF-α, thus reducing the infiltration of inflammatory cells in the epidermis." (PMID 33967781, 2021). "The TNF-308 (rs1800629), TNF-238 (rs361525), and TNF-857 (rs1799724) variants have been associated with the risk of suffering from psoriasis and with the response to anti-TNFs in psoriasis and other autoimmune diseases, such as ankylosing spondylitis and Crohn’s disease." (PMID 34577605, 2021). "The influence of polymorphisms of TLR2 (rs4696480 and rs11938228), TLR5 (rs5744174), and TLR9 (rs352139) on treatment response has been demonstrated in Caucasian patients (from Denmark) diagnosed with moderate-to-severe psoriasis and treated with anti-TNF drugs (n = 376) and with UTK (n = 230)." (PMID 34577605, 2021). "Anti-IL-17 agents or TNF inhibitors improved the metabolic disorder when treat psoriasis." (PMID 34367173, 2021). "Inflammatory mDCs, also known as TNF/iNOS-producing DCs (Tip-DCs), are present in high numbers in psoriatic skin lesions than in the normal skin and play an important role in the pathogenesis of psoriasis." (PMID 34371756, 2021). "Notably, some inflammatory factors, such as IL-17 and TNF, can both mediate the occurrence of psoriasis and MetS." (PMID 34367173, 2021). "The SLCO1C1 rs3794271 (G > A, C) and PDE3A rs11045392 (T > A, C) polymorphisms are in linkage disequilibrium and have been evaluated in a study with 130 Spanish patients diagnosed with moderate-to-severe psoriasis and treated with anti-TNF medication (n = 130)." (PMID 33921427, 2021). "The authors suggested that the levels of TNF-α copies in cfDNA might be a biomarker for severity in psoriasis patients, but further larger studies are needed to check its clinical potential." (PMID 33672659, 2021). "Accordingly, BZRAs may elevate the levels of some factors, such as IL-8, TNF-α VEGF, associated with the development of psoriasis." (PMID 34290604, 2021). "In addition, betulinic acid attenuated psoriatic skin inflammation in a murine model of imiquimod-induced psoriasis via downregulation of pro-inflammatory mediators IL-6 and TNFα." (PMID 34314383, 2021). "Macrophages in psoriasis driven by activating IL-36γ and IL-36R produced IL-23 and TNF-α." (PMID 34675805, 2021). "Several pro-angiogenic cytokines, such as IL-6, TNF-α, and IL-17, are up-regulated in psoriatic lesions, which may contribute to the increase in blood vessel formation in psoriasis patients." (PMID 33995368, 2021).
psoriasis (continued). "In psoriasis, IL-27 can both be responsible for disease onset itself, inducing Th1 lymphocytes, and can suppress the inflammation when TNF-α is upregulated, suggesting that manipulation of IL-27 in psoriasis could be beneficent." (PMID 34068473, 2021). "Although the abnormality of T-lymphocytes in psoriatic lesions and the inflammatory role of TNF-α have been associated with the pathogenesis of psoriasis, the cause of excessive keratinocyte proliferation is not completely understood." (PMID 35056961, 2021). "Their role in psoriasis is not fully known; however, it is thought that they contribute to the pathogenesis by stimulating adaptive immunity, presenting antigens to T lymphocytes, and secreting inflammatory products, particularly TNF-α, IL-12, and IL-23." (PMID 34769005, 2021). "TNF-a, which has an essential effect on the inflammatory process in psoriasis, may be involved in the pathogenesis of neurodegenerative diseases." (PMID 34039314, 2021). "However, a second pericyte population has been identified in skin from patients with atopic dermatitis and psoriasis; these pericytes have a proposed role in leukocyte recruitment and TNFα-mediated signaling." (PMID 34124060, 2021). "However, the transcription of genes of key inflammatory mediators, such as S100 antimicrobial peptides, IL-6, and TNFα, which act synergistically to maintain an inflammatory response in psoriasis, can be activated by both sets of cytokines." (PMID 34877506, 2021). "In addition, multiple biologic agents (including monoclonal antibodies targeting IL-17, tumor necrosis factor-α, and IL-12/23) are available for the treatment of moderate to severe psoriasis." (PMID 34421919, 2021). "Among T lymphocyte-derived cytokines related to psoriasis, TNF-α is the main cytokine trigger of PI3Kδ expression, although IL-22 also sustains PI3Kδ levels in human keratinocytes, supporting a role for PI3Kδ in proliferation and de-differentiation processes induced by IL-22 in diseased skin." (PMID 34685616, 2021). "TNF-α, a major mediator of psoriasis pathogenesis, has been shown to induce the expression of IL-6." (PMID 34158537, 2021). "This technique has also been used to deliver the anti‐TNF‐α drug etanercept for topical psoriasis." (PMID 34589595, 2021). "In vivo studies showed that PSORI-CM02 markedly reduced angiogenesis in the skin of mice with IMQ-induced psoriasis, while significantly rebalancing antioxidant/oxidant levels; inhibiting the production of IL-6, TNF-α, IL-17A, and IL-17F; and repressing the synthesis of angiogenic mediators." (PMID 33995368, 2021). "Classical psoriasis is a T-cell mediated autoimmune disease that is primarily driven by autoreactive T cells that produce high levels of interleukin-17 (IL-17) in response to IL-23 and tumor necrosis factor-alpha (TNF-α)." (PMID 32382290, 2020). "However, most studies have reported that the risk of reactivation of HBV seems to be relatively low in patients with psoriasis treated with TNF inhibitor." (PMID 32987907, 2020). "It is reasonable to speculate the influence of genetic factors predisposing to paradoxical psoriasis, and specifically being involved in innate immunity pathways, in particular in pDC activation and/or type I IFN and TNF‐α signaling." (PMID 31577850, 2020). "Also, the initiation of anti-tumor necrosis factor therapy (n = 16) reduced the severity of psoriasis (p < 0.001), levels of GlycA (463.7 ± 92.5 vs. 370.1 ± 78.5; p < 0.001) and vascular inflammation (1.93 ± 0.36 vs. 1.76 ± 0.19; p < 0.001)." (PMID 33262910, 2020). "In future, we hope to address whether chrysin can reverse the inhibition of TNF-α, IL-17A, or IL-22-induced differentiation in keratinocytes in psoriasis." (PMID 32076123, 2020). "IGFL is induced by TNF-α and was shown to be increased in skin in psoriasis and wounding models." (PMID 32928964, 2020). "Blocking TNFα is a highly effective therapy for psoriasis patients." (PMID 33643287, 2020).
psoriasis (continued). "The pathophysiology behind the paradoxical appearance of psoriasis is not well understood: anti-TNF agents induce the activation of autoreactive T cells and increase interferon-α activity, leading to high levels of pro-inflammatory cytokines (interleukin 12, 17, and 23)." (PMID 32842528, 2020). "TNF-α is an important cytokine in psoriasis, it plays a multi-faceted role." (PMID 32708987, 2020). "TNF and IL-17 are relevant cytokines in the pathogenesis of psoriasis and of OP, and are revealed as possible therapeutic targets on which to act to suppress the hyperreactivity of the immune system and restore the balance between resorption and bone formation." (PMID 32635380, 2020). "That the tumor necrosis factor-α (TNF-α) and IL-23/IL-17A axes appear to be major drivers in the pathogenesis of psoriasis is underscored by the excellent response of psoriasis to biologics targeting TNF-α, IL-23, and IL-17A, although a difference exists in their efficacy." (PMID 32070069, 2020). "Infliximab isa monoclonal immunoglobulin G1 antibody to tumor necrosis factor alfa (TNF-α)and is used for the treatment of several inflammatory diseases, such as rheumatoidarthritis, ankylosing spondylitis, psoriasis, Crohn’s disea se, and Behçetdisease (off-label)." (PMID 32756784, 2020). "Emerging evidence from clinical trials has shown that monoclonal antibodies against IL-23, IL-17, and tumor necrosis factor are effective in the treatment of patients with psoriasis, atopic dermatitis, hidradenitis suppurativa, pityriasis rubra pilaris, pemphigus, and systemic sclerosis." (PMID 33281823, 2020). "Moreover, polymorphisms in the TNF-α promoter, such as rs1799964 and rs1800629, are known to be involved in modulating anti-TNF-α response in classical psoriasis and IBD." (PMID 33114187, 2020). "In fact, other than controlling the expression of type I IFNs in pDCs, TNF‐α might negatively regulate these molecules in keratinocytes, which notoriously also contribute to the induction of innate immunity pathways in early psoriasis." (PMID 31577850, 2020). "Furthermore, TNF-α antagonists were reported to disrupt Th1, Th17, and Th22 pathways, resulting in the clinical improvement of psoriasis." (PMID 32280718, 2020). "Furthermore, TNF-α is involved in the development of psoriasis and hyperproliferation of keratinocytes and enhances Th17 cell generation." (PMID 32316255, 2020). "Chronic inflammation and persistent release of TNF-α and IL-6 are both produced by adipose tissues and may contribute to the comorbidities of psoriasis and metabolic syndrome." (PMID 32823524, 2020). "Groups that have been treated with Dysidea avara methanolic extracts are most active in reducing symptoms of induced psoriasis by decreasing amounts of IL-22, IL-17A, TNF-α, and decreasing neutrophils” infiltration into the epidermis, which is important in psoriasis’s pathogenesis." (PMID 33253155, 2020). "Alternatively, this effect might be a paradoxical effect; for example, TNF-alpha inhibitors aggravated psoriasis, when they should have improved it." (PMID 32560321, 2020). "Enhanced expression of sCD200 in psoriasis could be a consequence to the ongoing inflammatory response, characterized by an increased release of TNFα and INFγ, both of which are potent inducers of CD200 expression." (PMID 32203537, 2020). "In this study, we explored several factors that contributed to psoriasis, such as TNF-α, IL-17A, and IL-22 and found that chrysin could ameliorate the inflammatory reactions induced by these factors." (PMID 32076123, 2020). "Th17 cells exert an effect by secreting IL-17A, IL-17F, IL-26, and TNF in psoriasis, forming a feedforward inflammatory network with KCs, activating STAT-1 and NF-κB signaling pathway, and inducing keratinocytes (KCs) to secrete several pro-inflammatory factors." (PMID 32377228, 2020).
psoriasis (continued). "Our results revealed significantly increased levels of the tested proinflammatory cytokines and a decrease in IL-10 concentration in unstimulated and stimulated saliva of psoriasis patients with normal salivation (except for TNF-α in NWS and INF-γ in SWS) and hyposalivation compared to the controls." (PMID 32164227, 2020). "Finally, investigations in the xenograft models of psoriasis have indicated the significance resident T cells in the evolution of psoriasis and their role in the production of TNF-α in these lesions." (PMID 32695942, 2020). "In order to investigate the role played by IL-17A and IL-36 cytokines in the activation of skin EC, expression of IL-17 and IL-36 receptors by HDMECs was analyzed, together with possible modulation of this expression by inflammatory cytokines present in the psoriasis microenvironment, such as TNF-α." (PMID 32352958, 2020). "Furthermore, TNF-α can act synergistically with IL-17 to promote inflammation in psoriasis, while IL-17 and IFN-γ can act synergistically to produce pro-inflammatory cytokines in keratinocytes." (PMID 32958733, 2020). "The TNF-α-308 polymorphism is one of the most important TNF polymorphisms in human disease susceptibility such as; autoimmune hepatitis, type 1 and type 2 diabetes mellitus, acne vulgaris, psoriasis, and Sjogren's syndrome." (PMID 33370782, 2020). "Taken together, our findings provide insights into the regulation of the epidermal cell death and inflammation and warrant future analyses of the impact cFLIP and TNF in a number of inflammatory skin pathologies including psoriasis and toxic epidermal necrolysis." (PMID 33238518, 2020). "Interestingly, treatment of psoriasis with anti-TNF therapy led to a decrease in GlycA levels and vascular inflammation." (PMID 32012794, 2020). "Recently, although TNF inhibitors were been widely used and the traditional treatment strategies of psoriasis were changed, but some refractory patients still might have inhibitor resistance." (PMID 32724829, 2020). "TNF-α inhibitors show beneficial effects both on psoriasis and IBD." (PMID 32987907, 2020). "Besides keratinocytes, fibroblasts and dermal mast cells are important sources, as shown for TNF-α in psoriasis and atopic dermatitis, and for IL-6 in psoriasis." (PMID 32927792, 2020). "In the future, it will be necessary to extend the analysis of psoriasis‐related SNPs to a larger cohort of HS patients developing psoriasiform reactions, but also in a population successfully responding to anti‐TNF‐α treatment, to identify differences in the genetic background of the patients." (PMID 31577850, 2020). "The significant decrease or completely absent of LC migration in early‐onset psoriasis is mainly caused by IL‐1β, TNF‐α and contact allergen." (PMID 32916775, 2020). "We determined the mRNA expression levels of several inflammatory cytokines that are important in psoriasis (TNF-α, IL-23p19, IL-17A, IL-22, IFN-α, IL-1β, IL-6, and IL-10) and a chemokine that promotes the migration of neutrophils (CXCL2) using quantitative real-time PCR." (PMID 32752186, 2020). "We investigated the immune regulation of TNFAIP3 in the pathogenesis of psoriasis and determined whether it is involved in the antipsoriatic effect of TNF-α antagonists." (PMID 32280718, 2020). "It will be important to evaluate the effects of anti‐TNF‐α therapy on keratinocytes in paradoxical psoriasiform reactions, especially in terms of type I IFN production, to identify new pathogenic mechanisms involved in the early phase of psoriasis." (PMID 31577850, 2020). "In addition to being a skin barrier, keratinocytes release inflammatory cytokines, such as TNF; express IL-17 receptors; and participate in the initiation and amplification of psoriasis." (PMID 32013194, 2020).